NR3C1 (nuclear receptor subfamily 3 group C member 1)
Diseases named in the same sentence as NR3C1 in open-access papers (continued):
Sharing a sentence is not in itself a finding about the gene and the disease.
tumor (continued). "We used mice corticotroph tumor AtT-20/D16v-F2 cells for in vitro experiment and initially verified whether these cells do express Nr3c1 and Nr3c2 genes using deposited RNAseq data from a previous experiment on AtT-20 cells (GSE132324; Gene Expression Omnibus) and qRT-PCR." (PMID 35270010, 2022). "Additionally, naringenin could promote differentiation and maturation of DC among tumor microenvironment through regulating FKBP4/NR3C1/NRF2 signaling pathway." (PMID 35087512, 2021). "Therefore, NR3C1 is important for inhibiting tumor progression." (PMID 29636077, 2018). "Mechanistically, NR3C1 deletion relieved cortisol-mediated suppression of PI3K-AKT-NF-κB signaling, restored anti-tumor activity, and markedly reduced hypoxic stress." (PMID 41956993, 2026). "Other upregulated genes included NR3C1, NMB, and COTL1, which are coordinately expressed with PDCD1, CXCL13, and ENTPD1 by tumor infiltrating CD4+ T cells." (PMID 40956619, 2025). "In clear cell renal cell carcinoma, NR3C1 knockdown activates endoplasmic reticulum stress and mitophagy via the ATF6-PINK1/BNIP3 pathway, suppressing tumor proliferation and migration." (PMID 41050683, 2025). "Primarily, intermediate TEx was concomitant with the accessibility of NR3C1 and NR4A1 motifs, the direct downstream factors of tumor cell receptor signaling." (PMID 38918817, 2024). "NR3C1, STAT1, and STAT3 showed higher expression levels in tumor tissues, and all of these transcription factors were shown to be associated with T cell depletion status and terminal T cells." (PMID 38604154, 2024). "We found that the activities of target genes regulated by NR3C1, STAT1, and STAT3 were higher in tumor tissues, implying that NR3C1, STAT1, and STAT3 played critical regulatory roles for the development of CTLA4+ T cell subsets." (PMID 38604154, 2024). "In CD patients NR3C1 and NR3C2 levels were negatively correlated with morning plasma ACTH levels and tumor size." (PMID 37065760, 2023). "In order to verify the reliability of five genes in predicting prognosis, by using HPA to detect protein expression levels in normal and tumor tissues, we found that there were significant differences in ANLN and NR3C1 between tumor tissues and normal tissues." (PMID 35548187, 2022). "A somatic frameshift mutation in the glucocorticoid receptor gene (NR3C1) resulting in premature termination of the coding sequence has been described in a patient with Nelson’s syndrome, which may contribute to tumor development by reducing glucocorticoid feedback on tumor cells." (PMID 32201880, 2020). "The global O-GlcNAcylation omics mapped the O-GlcNAcylated sites and proteins in resistant and nonresistant tumor cells, showing that NR3C1 is highly O-GlcNAcylated at Thr299 in response to chemotherapy." (PMID 40740652, 2025). "On the other hand, the expression of genes TOP1, EGFR, STAT3, NR3C1, VEGFA, and AR was upregulated, which could promote tumor cell growth." (PMID 38297292, 2024). "NR3C1 amplification, along with IL-6 and SRPX suppressions, were detected in tumor." (PMID 36675190, 2023). "In this study, we showed that naringenin, a flavonoid shown to have anti-tumor effects in various carcinomas in other studies, suppressed both autophagy and proliferation via new-found FKBP4/NR3C1/NRF2 signaling pathway in luminal A and basal-like subtype of BC cells." (PMID 35087512, 2021). "Finally, a negative correlation between GR and tumor size, and higher NR3C1 expression was demonstrated in densely granulated tumors." (PMID 41303810, 2025). "Interestingly, NR3C1 was co-expressed with MRC1 and CD163 in M03 cells, suggesting that NR3C1 may play a role in inhibiting immune-mediated tumor cell killing." (PMID 40260248, 2025). "As regards the glucocorticoid receptor, NR3C1 expression was evenly distributed among tumoral specimens, without significant differences according to tumor size or surgical outcomes." (PMID 27220856, 2017).
cancer (156 papers, 2007 to 2026). A tumor composed of atypical neoplastic, often pleomorphic cells that invade other tissues. "As a first step, we examined the glucocorticoid receptor encoding NR3C1 expression at the RNA and GR protein levels across different normal tissues and cancer types, including normal and cancerous breast samples, using high-throughput data." (PMID 36899920, 2023). "We have demonstrated that in the presence of enzalutamide or darolutamide, AR is enriched in the distal elements of cancer-related genes such as NR3C1 (encoding GR) and SLC7A11, and upregulates their expression in both ADPC and CPRC cell models." (PMID 35864113, 2022). "Our analysis of 10 cancer gene microarray datasets from the Oncomine database revealed that GR (encoded by NR3C1 gene) transcript was consistently downregulated in prostate tumors compared to normal prostate tissues, in agreement with the previous reports." (PMID 30305646, 2018). "In the present study, we assessed genetic associations of the functional Bcl-1 polymorphism (rs41423247) of NR3C1 gene, with death by suicide in cancer patients, in particular suicide within the first year of diagnosis." (PMID 27401254, 2016). "In addition to several oncogenic pathways, such as ErbB and Rap1 signaling pathways, NR3C1‐bound genes were enriched in the Wnt signaling pathway, which is strongly associated with cancer cell stemness and multidrug resistance." (PMID 39731339, 2025). "Meanwhile, the NR3C1 gene, which encodes the glucocorticoid receptor, acts as a critical mediator of cellular responses to stress and inflammation—two processes intimately involved in cancer progression." (PMID 40608705, 2025). "Our findings suggest that the NR3C1 Bcl-1 polymorphisms may be involved in the susceptibility to suicide within the first year after cancer diagnosis among cancer patients in Korean population." (PMID 27401254, 2016). "Nr3c1 has a function in the regulation of muscle hypertrophy and strength in response to resistance training; however, the role of Nr3c1 in the development of muscle wasting associated with cancer is still unknown." (PMID 31013615, 2019). "Inhibition of NR3C1 O-GlcNAcylation via Thr299 mutant or knockout of NR3C1 facilitates ferroptosis and improves chemosensitivity of resistant cancer cells in vitro and in vivo." (PMID 40740652, 2025). "Targeted inhibition of GFPT1 and NR3C1 O-GlcNAcylation resensitizes the resistant cancer cells to chemotherapy in BCa orthotopic and xenograft mouse models." (PMID 40740652, 2025). "We further analyzed NR3C1 in pan-cancer patients receiving aPD-L1/aPD-1 therapy and found that NR3C1 expression was positively correlated with both PFS and OS." (PMID 40260248, 2025). "We identified 1,186 O-GlcNAcylated sites on 315 proteins, of which NR3C1 was highly O-GlcNAcylated in GC-resistant cancer cells." (PMID 40740652, 2025). "A growing number of evidences indicate the important roles of NR3C1 in cancer proliferation, metastasis, and drug resistance." (PMID 40740652, 2025). "Overall, miR-1270 inhibition reinforced NR3C1 expression and thus attenuated the anti-cancer effects of NR3C1 knockdown on PC cell phenotypes." (PMID 36797317, 2023). "As a critical regulator of glucocorticoid hormone effects, NR3C1 can alter gene expression in target cells and tissues, potentially leading to cancer." (PMID 36589842, 2022). "There were also associations unique to each cancer type, including USF1 and SMAD1 for BRCA, FOXF2 for HNSC, and NFE2L2 and NR3C1 for UCEC." (PMID 28139702, 2017). "Our previous data showed that glucocorticoid receptor (GR/NR3C1) expression is higher in primary prostate normal and cancer stem cells, compared to CB cells from normal and cancer primary cultures." (PMID 27340920, 2016).
cancer (continued). "We examined genetic associations of the functional Bcl-1 polymorphism of (rs41423247) neuron-specific glucocorticoid receptor (NR3C1) gene, with death by suicide in cancer patients." (PMID 27401254, 2016). "These novel SNPs in the KAT5 and NR3C1 genes warrant confirmation, and additional functional studies are needed to assess the functional consequences of the mutations and their relationship to cancer, such as whether the SNPs would mimic the epigenetic regulations of these genes." (PMID 23940558, 2013). "NR3C1 induces reversible cancer cell dormancy by activating growth factor survival signaling." (PMID 40740652, 2025). "Circ_0128846 exerted these cancer-promoting effects by targeting the miR-1270/NR3C1 network, at least in part, hinting that the repression of circ_0128846 might be helpful to PC treatment." (PMID 36797317, 2023). "Previous studies have suggested that the marker of carcinomas with microsatellite instability were hypermethylated NR3C1, its mechanism in the development of CRC may be related to apoptosis, and further experimental evidence is needed." (PMID 33330631, 2020). "While more remains to be investigated on psychosocial and immune cell response and gene expression, current data on human models do implicate appropriate gene expression via the CTRA and NR3C1 gene in the SNSS as observed in meditation, yoga and thai-chi, implicated in malignant neoplasm remission." (PMID 31717711, 2019). "Notably, for all the seven HUB nodes of the linking region between three cancer networks, mutations were found in all three cancers (BlC, KiC, PrC) with the higher frequency percentages identified for four nodes: MAP3K7, NR3C1, PABPC1 and CTNNB1." (PMID 29991691, 2018). "In a recent study of children who were removed from their parents due to abuse or neglect, a reduction in methylation of NR3C1, an inflammatory regulation gene, as well as differential methylation of cancer related pathways was found in children with ACEs compared to controls." (PMID 24386563, 2013). "In addition, we observed that NR3C1 knockdown reinforced Bax expression and impaired Bcl-2 expression in cancer cells, while miR-1270 inhibitor reintroduction attenuated Bax expression that was reinforced by NR3C1 knockdown and recovered Bcl-2 expression that was impaired by NR3C1 knockdown." (PMID 36797317, 2023). "Importantly, since GATA2 functions upstream of NR3C1 and other enzalutamide-induced cancer-promoting genes (e.g. SLC7A11 and LAMP3), targeting GATA2 maybe a better strategy for improving AR-targeted therapy by enzalutamide." (PMID 31501863, 2019). "To find a possible link between these three cancers subjected to arsenicals exposure, we merged the three networks and identified seven HUB nodes (RXRA, MAP3K7, NR3C1, PABPC1, NDRG1, RELA and CTNNB1) of the linking region between three cancer networks." (PMID 29991691, 2018). "Overall, gene methylation frequencies were higher among MSI than among MSS carcinomas, and were statistically significant for CRABP1, MLH1, NR3C1, RUNX3, and SCGB3A1 (P ≤ 0.0001, P ≤ 0.0001, P = 0.001, P ≤ 0.0001, and P = 0.03, respectively)." (PMID 19117505, 2008). "Hypermethylated CRABP1, MLH1, NR3C1, RUNX3, and SCGB3A1 were shown to be identifiers of carcinomas with microsatellite instability." (PMID 19117505, 2008). "This analysis validated the identification of genes that could be specific to cancer biology, such as IL7R, JUN, NR3C1 in Ba/Sq subtype, NPAS2, FOXQ1, GRHL3 in Luminal samples, or CDKN2C, FOXJ1, MEIS2, FGFR3 in both subtypes." (PMID 36944729, 2023). "Interestingly, the FOXA1-mediated repression of NR3C1 i.e. the inverse correlation between the two TFs, is not restricted to PCa but can be observed in other cancers." (PMID 38015476, 2024). "Lower NR3C1 expression levels were found in cancer cells compared to normal tissues of breast." (PMID 36468011, 2022). "Finally, methylation of CRABP1, MLH1, NR3C1, RUNX3, and SCGB3A1 were identifiers of MSI carcinomas." (PMID 19117505, 2008).
cancer (continued). "Then, a pan-cancer differential expression analysis was performed, and we found that genes such as CXCL13, ITM2A, NR3C1, SRGN, COTL1, and PDCD1 were significantly up-regulated in SC-2 cells compared with other cells in at least five cancer types, but not in SC-10 cells." (PMID 36049666, 2023).
psychiatric disorder (36 papers, 2014 to 2026). A disorder characterized by behavioral and/or psychological abnormalities, often accompanied by physical symptoms. "The identification of miR-20b-3p as a key regulator of NR3C1 provides new insights into stress-induced molecular changes and suggests potential therapeutic targets for stress-associated psychiatric disorders." (PMID 41240141, 2025). "CpGs previously associated with stress and psychiatric disorders, including CpGs in NR3C1 and FKBP5, replicates poorly across studies and have so far failed to translate into reliable clinical tests." (PMID 31040859, 2019). "One possible link between DCAF6, associated with this LD block by eQTL, and susceptibility to psychiatric disorders is that its protein binds NR3C1, of which changes in methylation are linked with childhood abuse." (PMID 27798116, 2017). "Childhood maltreatment was also associated with increased methylation of NR3C1 promoter in the blood of patients affected by psychiatric disorders including MDD." (PMID 26005424, 2015). "Likewise, in two samples with psychiatric disorders, childhood maltreatment was associated with greater NR3C1 methylation." (PMID 33608499, 2021). "We then examined methylation in a shortlist of genes that were previously associated with early life stress and psychiatric disorders as well as placental functioning: Ank3, Avp, Avpr1a, Avpr1b, Bdnf, Cacna1c, Cyp11b1, Cyp11b2, Fkbp5, Hsd11b1, Igf2, Morc1, Nr3c1, Oxt, Oxtr, Pclo, Slc6a4." (PMID 30655507, 2019). "Interestingly, we found that 10Hz flicker mitigated stress-induced changes in transcription of microglial receptors P2ry12 and stress associated receptors such as Nr3c1 and Tlr4, as well as microglial Igfbp2, a key gene implicated in affective and psychiatric disorders." (PMID 40791511, 2025). "Methylation of exon 1 (F) of the glucocorticoid receptor gene NR3C1 is associated with early stress exposure and risk of developing psychiatric disorders." (PMID 38249586, 2023). "Targeting NR3C1 methylation patterns may provide therapeutic potential for stress-related psychiatric disorders." (PMID 41234420, 2025). "Psychiatric disorders may contribute to alterations in methylation of NR3C1 to a lesser degree, possibly via effects of these disorders on behavioral and physiological factors involved in stress responses." (PMID 27378548, 2016). "Epigenetic dysregulation of NR3C1 and FKBP5 have repeatedly been observed in psychiatric disorders following early life stress." (PMID 31040859, 2019). "Serena’s research found that after childhood trauma, the promoter region of the glucocorticoid receptor gene (NR3C1) exhibited a characteristic of high methylation, significantly correlating with an enhanced sensitivity to stress responses and a greater likelihood of mental illnesses." (PMID 40557138, 2025).
infection (20 papers, 2009 to 2025). The state of being infected such as from the introduction of a foreign agent such as serum, vaccine, antigenic substance or organism. "Examination of the ontologies enriched in this set of up-regulated genes showed genes known to play a role in infection processes, including NR3C1, PTPRC, SFRS1, SFRS5, SMAD3, C3 and DDX58." (PMID 22363497, 2012). "Despite lower mRNA for NR3C1 during infection (-1.33-fold), we observed up-regulation of ANXA1 (1.38-fold change)." (PMID 19925655, 2009).
cardiovascular disease (7 papers, 2010 to 2022). "However, other investigators have not found NR3C1 +363 A>G genotype differences with body composition, blood pressure, insulin resistance, and cardiovascular disease." (PMID 26821164, 2016).
infectious disease (6 papers, 2007 to 2022). A disorder directly resulting from the presence and activity of a microbial, viral, or parasitic agent in humans. "We observed that top functions these genes involved are RNA post-Transcriptional Modification (CLP1 TSEN2 and TSEN54) and infectious disease and inflammatory disease (NR3C1, PPP3CC, and PPP3R1)." (PMID 21172007, 2010).
neurological disorders (6 papers, 2015 to 2025). "Abnormal expression of NR3C1 in the cerebral cortex may have a relevance for neurological disorders given the predicted contribution to regulation of CDK5R1." (PMID 28720872, 2017).
metabolic disorders (5 papers, 2016 to 2026). "Our above data indicated that OVX and ADX exerted their actions on regulating the AT remodeling and resultant metabolic disorders, likely by principally potentiating the Pparg signaling and inactivating the Nr3c1 signaling, respectively." (PMID 36768630, 2023).
adenocarcinoma (3 papers, 2007 to 2021). A common cancer characterized by the presence of malignant glandular cells. "We demonstrate that overexpression of glucocorticoid receptor (GR) NR3C1 increased RANKL promoter activity in human osteosarcoma, cervical cancer (2-fold) and adenocarcinoma cells (4.5-fold)." (PMID 33494362, 2021).
heart disease (2 papers, 2017 to 2021). "NR3C1 was also reported to be one of the driver genes of PTSD in a study involving a search for the genes causing PTSD-mediated heart diseases." (PMID 29322921, 2017).
intestinal disorder (1 paper, 2024). A non-neoplastic or neoplastic disorder that affects the small or large intestine. "For instance, Faecalibacterium prausnitzii, which is known for its abundance in the healthy human microbiota and depletion in various intestinal disorders, including CRC, was associated with the methylation of PPFIA2, NR3C1, and EXO1." (PMID 38840170, 2024).
NR3C1 also shares sentences with these, for which no sentence is quoted: Hyperglycemia (20 papers); triple-negative breast carcinoma (11); glioma (10); hepatocellular carcinoma (9); lymphoma (8); chronic obstructive pulmonary disease (7); steatosis (7); injury (6); adrenal hyperplasia (5); Hepatic fibrosis (5); Hepatic steatosis (5); neurodegenerative disease (5); Allergy (4); Alzheimer disease (4); cardiac hypertrophy (4); diabetic kidney disease (4); hypokalaemia (4); neuroblastoma (4); viral infection (4); atopic dermatitis (3); B-cell chronic lymphocytic leukemia (3); chronic kidney disease (3); fibrosis (3); generalized anxiety disorder (3); hematological disease (3); Huntington disease (3); Impaired glucose tolerance (3); influenza (3); keloid (3); kidney disease (3).
A further 204 diseases each share a sentence with NR3C1 in 3 papers or fewer.